MSL1 (MSL complex subunit 1)
Description:
Non-catalytic component of the MSL histone acetyltransferase complex, a multiprotein complex that mediates the majority of histone H4 acetylation at 'Lys-16' (H4K16ac), an epigenetic mark that prevents chromatin compaction. The MSL complex is required for chromosome stability and genome integrity by maintaining homeostatic levels of H4K16ac. The MSL complex is also involved in gene dosage by promoting up-regulation of genes expressed by the X chromosome (By similarity). X up-regulation is required to compensate for autosomal biallelic expression (By similarity). The MSL complex also participates in gene dosage compensation by promoting expression of Tsix non-coding RNA (By similarity). Within the MSL complex, acts as a scaffold to tether MSL3 and KAT8 together for enzymatic activity regulation. Greatly enhances MSL2 E3 ubiquitin ligase activity, promoting monoubiquitination of histone H2B at 'Lys-34' (H2BK34Ub). This modification in turn stimulates histone H3 methylation at 'Lys-4' (H3K4me) and 'Lys-79' (H3K79me) and leads to gene activation, including that of HOXA9 and MEIS1.
Synonyms: MSL-1; hMSL1; DKFZp686P24239
Tractability: PROTAC: UniProt records ubiquitination sites on it; ubiquitination databases record sites on it; its protein half-life has been measured.
Gene: Protein-coding gene on chromosome 17 (40,121,971 to 40,136,917, forward strand). Ensembl gene ENSG00000188895.
Subcellular location: Nucleus; Nucleus, nucleoplasm; Nucleus speckle
Subcellular location (Human Protein Atlas): Nucleoplasm; Nuclear speckles; Vesicles
Pathways (Reactome):
Chromatin organization: HATs acetylate histones
Gene Ontology:
Molecular function: protein binding; protein-macromolecule adaptor activity; chromatin binding
Biological process: positive regulation of DNA-templated transcription; chromatin remodeling
Cellular component: MSL complex; nuclear speck; nucleoplasm; nucleus
Genetic constraint (gnomAD): Loss-of-function variants: 19 observed, 55.42 expected, observed/expected ratio (o/e) 0.34, 90% interval 0.24 to 0.5. The upper end of that interval is the gene's LOEUF score, 0.5, which puts it in group 2 of 6, group 1 being the genes least tolerant of losing a copy. Missense variants: 655 observed, 743.5 expected, observed/expected ratio (o/e) 0.88, 90% interval 0.82 to 0.94. Synonymous variants: 337 observed, 305.94 expected, observed/expected ratio (o/e) 1.1, 90% interval 1.01 to 1.21.
Homologues: Orthologues: chimpanzee MSL1 (100% identical), macaque MSL1 (99% identical), pig MSL1 (99% identical), dog MSL1 (99% identical), rabbit MSL1 (99% identical), rat Msl1 (97% identical), mouse Msl1 (96% identical), guinea pig MSL1 (54% identical), tropical clawed frog msl1 (42% identical), zebrafish msl1b (32% identical), zebrafish msl1a (32% identical), Drosophila melanogaster msl-1 (19% identical), and 1 more.
Diseases named in the same sentence as MSL1 in open-access papers:
MSL1 is named in the same sentence as 15 diseases in open-access papers, as found by Europe PMC text mining. Sharing a sentence is not in itself a finding about the gene and the disease. The quoted sentences say what the papers report.
nasopharyngeal carcinoma (3 papers, 2021 to 2025). A carcinoma arising from the nasopharyngeal epithelium. "In nasopharyngeal carcinoma, PBK-mediated phosphorylation of MSL1 enhances CD276 transcription and facilitate immune evasion, implicating the MSL complex in tumor-associated immune regulation." (PMID 41409271, 2025). "In nasopharyngeal carcinoma, PBK-mediated phosphorylation of MSL1 enhances MSL complex occupancy at the CD276 promoter, driving transcriptional activation of CD276 and promoting immune evasion." (PMID 41409271, 2025).
colon cancer (2 papers, 2025). "In this study, we found that Erastin-induced ferroptosis in colon cancer cells significantly reduced MSL1 expression, suppressing the H4K16ac enzyme activity of the MOF/MSL complex and upregulating KCTD12 expression." (PMID 40221412, 2025). "To date, only one study has examined MSL1’s role in colon cancer, demonstrating that MSL1 knockdown enhances cisplatin-induced DNA damage, promote apoptosis in HCT116 cells, and thereby facilitates tumor cell elimination." (PMID 40221412, 2025). "Notably, in colon cancer cells, the ferroptosis inducer Erastin significantly suppressed MSL1 expression, leading to KCTD12 upregulation." (PMID 40221412, 2025). "Based on this, we hypothesize that MSL1 induces ferroptosis via SLC7A11 suppression, potentially inhibiting colon cancer progression through its interacting with KCTD12." (PMID 40221412, 2025). "Furthermore, we found that MSL1 downregulation, via modulation of KCTD12, suppresses the expression of key negative regulators of ferroptosis, SLC7A11 and GPX4, thereby promoting Erastin-induced ferroptosis in colon cancer cells." (PMID 40221412, 2025). "TIMER analysis confirmed a negative correlation between MSL1 and KCTD12 in colon cancer cells (cor = −0.339)." (PMID 40221412, 2025).
atopic asthma (1 paper, 2023). An asthma that is characterized by symptoms that are triggered by an allergic reaction caused by inhaled allergens such as dust mite allergen, pet dander, pollen and mold. "Notably, MSL1, MOCS2, NUPR1, and SGF29 interact with proteins encoded by three genes that are associated with post bronchodilator FEV1, atopic asthma and AD." (PMID 36574990, 2023).
breast invasive carcinoma (1 paper, 2025). "Notably, in breast invasive carcinoma (BRCA), patients with high MSL1 expression exhibited significantly worse survival compared with those with low expression (log-rank P = 0.02)." (PMID 41409271, 2025).
glioma (1 paper, 2016). A benign or malignant brain and spinal cord tumor that arises from glial cells (astrocytes, oligodendrocytes, ependymal cells). "As before we confirmed that mNS GSC have a higher expression level of the stem cell markers CXCR4, MELK, PTCH, CD44, CD133, MSl1 and CD90, while GL261 GDC expressed higher level of the differentiated glioma marker glial fibrillary acidic protein (GFAP)." (PMID 27073883, 2016).
ovarian carcinoma (1 paper, 2010). A malignant neoplasm originating from the surface ovarian epithelium. "Of genes examined in relation to risk of invasive ovarian cancer and risk of invasive serous ovarian cancer, only global variation in the MSL1 and PRPF31 genes was associated at p<0.05." (PMID 20111712, 2010). "More imminently, examination of promising SNPs within MSL1 among a larger set of serous invasive patients and controls and additional fine-scale mapping will assist in clarification of the importance of these genes to ovarian cancer susceptibility." (PMID 20111712, 2010).
pancreatic cancer (1 paper, 2013). "We used specific siRNAs to test whether Nupr1 and MSL1 partners are involved in pancreatic cancer cell survival after DNA damage induced by cisplatin treatments." (PMID 24205110, 2013).
serous ovarian cancer (1 paper, 2010). "Here, we found that inherited markers in the gene encoding MSL1, part of a complex that modifies the histone H4, may decrease risk of invasive serous ovarian cancer." (PMID 20111712, 2010). "Our data suggest that inherited variation in MSL1 may impact risk of invasive serous ovarian cancer and are consistent with findings that irregular H4 modifications may cause errors in chromatin folding and gene expression and are widespread in cancer phenotypes." (PMID 20111712, 2010).
cancer (8 papers, 2010 to 2025). A tumor composed of atypical neoplastic, often pleomorphic cells that invade other tissues. "High MSL1 expression was significantly associated with poorer overall survival in several cancer types." (PMID 41409271, 2025). "Bioinformatics analyses revealed that among MSL subunits, MSL1 displayed the most significant correlation with immune infiltration across multiple cancer types, with associated genes enriched in immune-related pathways." (PMID 41409271, 2025). "We, therefore, hypothesized that the poor prognosis observed in USH2A-mutated patients may be due to elevated MSL1 expression, which could protect cancer cells from the cytotoxic effects of chemotherapeutic agents." (PMID 40312292, 2025). "While studies suggest that MSL1 inhibition enhances chemotherapy-induced cytotoxicity in cancer cells, the underlying molecular mechanisms remain unclear." (PMID 40221412, 2025). "Moreover, MSL1 is highly expressed in various cancer tissues and has been implicated in tumor cell survival through multiple mechanisms." (PMID 40221412, 2025). "Bioinformatic analyses revealed strong correlations between MSL1 expression, immune cell infiltration, and enrichment of immune-related gene sets across multiple cancer types." (PMID 41409271, 2025). "Together, these findings identify MSL1 as a key epigenetic regulator of tumor immune evasion and highlight it as a potential therapeutic target for enhancing cancer immunotherapy efficacy." (PMID 41409271, 2025). "MSL1 expression correlates with immune infiltration across cancers, and its deletion markedly reduces CD274 expression." (PMID 41409271, 2025). "To further explore the role of MSL1 in the tumor microenvironment, we examined the relationship between somatic copy number alterations (SCNA) of MSL1 and immune cell infiltration across cancers using TIMER 2.0." (PMID 41409271, 2025). "Collectively, these findings demonstrate that MSL1 acts as a positive regulator of CD274 expression across diverse cancer cell lines, as evidenced by reciprocal and consistent results from both gain- and loss-of-function experiments." (PMID 41409271, 2025). "MSL1, having a DNA-repairing activity, can suppress DNA damage-induced apoptosis to promote cancer cell survival." (PMID 37031243, 2023). "To test this possibility in a broader oncogenic context, we analyzed the correlation between MSL1, MSL3, and CD274 expression across multiple cancer types using the TIMER2.0 database." (PMID 41409271, 2025). "For instance, DNA damage–induced alternative polyadenylation can elevate MSL1 expression through PCF11, thereby protecting cancer cells from apoptosis." (PMID 41409271, 2025). "Given the robust effects of MSL1 in HEK293T cells, we further evaluated its role in multiple cancer cell lines." (PMID 41409271, 2025). "Collectively, these results identify MSL1 as a key epigenetic regulator of CD247 expression and a potential therapeutic target for enhancing the efficacy of cancer immunotherapy." (PMID 41409271, 2025). "Collectively, our findings describe a novel PBK/MSL1/CD276 signaling axis, which may play an important role in immune evasion of NPC and may be targeted for cancer immunotherapy." (PMID 33431797, 2021). "We have noticed that HORMAD1 depletion leads to reduced MSL1 levels and specifically decreases H4K16Ac levels (but not global Histone H4 acetylation in cancer cells (data not shown)." (PMID 30333500, 2018).
tumor (3 papers, 2024 to 2025). "Together, these results indicate that MSL1 modulates tumor immunity by influencing CD274 expression and its associated signaling networks." (PMID 41409271, 2025). "GeneCards enrichment analysis further indicated that MSL1-associated genes are enriched in immune-related pathways, supporting the notion that MSL1 contributes to shaping the tumor immune microenvironment." (PMID 41409271, 2025). "Together, these findings suggest a previously unrecognized association between MSL1 and CD274 (PD-L1), highlighting a potential epigenetic link between the MSL complex and tumor immune regulation." (PMID 41409271, 2025). "Elucidating the mechanisms by which MSL1 regulates immune checkpoints may thus provide new insights into tumor immune regulation and identify potential therapeutic targets to improve patient outcomes." (PMID 41409271, 2025). "While MSL1 is highly expressed in various tumors, its role in tumor progression and cell death remains unclear." (PMID 40221412, 2025). "Collectively, these findings indicate that MSL1 SCNAs may contribute to tumor immune evasion by modulating immune cell infiltration within the tumor microenvironment." (PMID 41409271, 2025). "Increasing evidence indicates that MSL1 plays a regulatory role in tumor biology." (PMID 41409271, 2025). "Overexpression of MSL1 significantly increased BIRC3, an anti-apoptotic factor, and HLA-A, a class I HLA molecule associated with antigen presentation, suggesting that MSL1 modulates CD274-dependent downstream signaling, potentially affecting apoptosis and the tumor microenvironment." (PMID 41409271, 2025). "Significant correlations were observed, with Spearman coefficients ranging from 0.031 to 0.526 (all p < 0.05), supporting the notion that MSL1 and MSL3 cooperatively regulate CD274 expression and contribute to tumor immune escape." (PMID 41409271, 2025).
infection (2 papers, 2020 to 2022). The state of being infected such as from the introduction of a foreign agent such as serum, vaccine, antigenic substance or organism. "Loss of Hda1 causes defects in multiple virulence-associated phenotypes similar to MSL1 deletion, reduced survival in murine macrophages, and decreased virulence in a murine infection model." (PMID 32527036, 2020). "In Cryptococcus, Msl1 is required for multiple virulence-associated phenotypes, including thermotolerance, cell wall stability, and melanin production, as well as full virulence in a murine infection model." (PMID 32527036, 2020).
MSL1 also shares sentences with these, for which no sentence is quoted: breast carcinoma (2 papers); cervical cancer (1); ileocolitis (1); prostate carcinoma (1).